LGALS3 (galectin 3)
Diseases named in the same sentence as LGALS3 in open-access papers (continued):
Sharing a sentence is not in itself a finding about the gene and the disease.
colorectal cancer (continued). "C4.4A expression was compared with the expression of EpCAM, galectin-3 and CO-029, which have been described as reliable markers in colorectal cancer." (PMID 17912244, 2007). "Moreover, not only siRNAs but also another miRNA molecule (miR-128) was able to sensitize HT-29 and SW620 colorectal cancer cells to chemotherapy and inhibit invasion potential these cells by decreasing the level of galectin-3." (PMID 30585294, 2019). "In contrast, a decrease in galectin-3 expression levels has also been found in colorectal cancer." (PMID 24303084, 2013). "The knockdown of galectin-3 expression induced apoptosis in human colorectal cancer cells." (PMID 24303084, 2013). "However, there are contradictory findings regarding the over- or under-expression of galectin-3 in human colorectal cancer." (PMID 24303084, 2013). "Therefore, additional statistical analyses on a potential correlation between C4.4A and galectin-3 expression and clinical parameters of grading, staging and disease-free survival were performed only for colorectal cancer and liver metastases derived thereof." (PMID 17912244, 2007). "This is in line with several reports on high-level expression of galectin-3 in colorectal cancer." (PMID 17912244, 2007). "In this study, we investigated the role of galectin-3 and carcinoembryonic antigen (CEA) in metastasis and survival of colorectal cancer (CRC) patients." (PMID 28977916, 2017). "Further, we observed synergistic correlation between serum galectin-3 and CEA levels with different stages of colorectal cancer patients." (PMID 28977916, 2017). "Next, we performed proximity ligation assay (PLA) and found that galectin-3 and CEA interacted with each other at the cell surface as well as in the cytoplasm of colorectal cancer cells." (PMID 28977916, 2017). "Also, some of the galectin family members (for example galectin-3) were found to be able to protect AML and colorectal cancer cells against apoptosis through mitochondrial stabilization in a B cell lymphoma protein (Bcl) 2-dependent manner." (PMID 31024310, 2019). "This suggests that therapeutic targeting of galectin-3 and CEA may have a synergistic effect on distal metastasis of colorectal cancer." (PMID 28977916, 2017). "It has been reported that Galectin-3 silencing inhibits epirubicin-induced ATP binding cassette transporters and activates the mitochondrial apoptosis pathway via β-catenin/GSK-3β modulation in colorectal carcinoma." (PMID 25260879, 2014). "Moreover, another miRNA molecule targeting galectin-3 (miR-128) also successfully downregulated galectin-3 protein levels in HT29 and SW620 colorectal cancer cell lines, but not mRNA levels." (PMID 30585294, 2019).
hepatocellular carcinoma (46 papers, 2011 to 2025). A malignant tumor that arises from hepatocytes. "More recently, another study has shown that galectin-3 deficiency reduces proliferation of hepatoma cells and increases their rate of apoptosis both in vitro and in vivo." (PMID 27242966, 2016). "Studies have shown that the overexpression of LGALS3 is closely associated with poor prognosis and tumor immune cell infiltration in hepatocellular carcinoma (HCC)." (PMID 40124784, 2025). "In a number of types of cancer including hepatocellular carcinoma (HCC) and triple-negative breast cancer, galectin-3 is highly expressed and implicated in the development of these cancers." (PMID 36481721, 2022). "Galectin-1 (Gal1) and galectin-3 (Gal3) are reported to be overexpressed in hepatocellular carcinoma (HCC)." (PMID 38612832, 2024). "In hepatocellular carcinoma, galectin-3 overexpression enhanced metastasis through the PI3K/AKT/GSK-3β/β-catenin signaling cascade." (PMID 34035807, 2021). "In hepatocellular carcinoma cells, galectin-3 silencing attenuated uPAR expression and inhibited the proliferation, migration and invasion." (PMID 32488496, 2020). "Galectin-3 expression can be used as a prognostic factor in hepatocellular carcinomas, since higher expression of galectin-3 in nuclei of cancer cells corresponds to a poorer prognosis." (PMID 32707678, 2020). "Several previous studies have confirmed altered galectin-3 expression in the liver and serum of patients with hepatocellular carcinoma, steatohepatitis and cirrhosis." (PMID 32707678, 2020). "Rho GTPase activity was reported to be decreased after Galectin-3 silencing in hepatocellular carcinoma cells." (PMID 29254179, 2017). "Other study also indicated the correlation between urokinase-type plasminogen activator receptor (uPAR) levels and galectin-3-decreased migration in hepatocellular carcinoma cells." (PMID 27242966, 2016). "An immunohistochemistry analysis revealed that galectin-3 was abundantly accumulated in the cytoplasm of Hepatocellular cancer cells." (PMID 25260879, 2014). "Galectin-3, a β-galactose-binding lectin, is widely recognized as a key mediator of inflammation and fibrogenesis and has been proposed as a prognostic biomarker for hepatocellular carcinoma." (PMID 40943431, 2025). "Its affinity towards Mac-2-binding protein (being produced by stromal cells of cirrhotic liver and correlating with hepatocellular carcinoma (HCC) via galectin-3/mTOR pathway enhancement) due to increased branching and decreased sialylation has been shown to be a promising biomarker of HCC." (PMID 39594740, 2024). "Galectin-3 is also upregulated in patients with cirrhosis and hepatocellular carcinoma, and its high expression correlates with immune infiltration, invasion, metastasis, and poor prognosis in hepatocellular carcinoma patients." (PMID 39194690, 2024). "LGALS3, a member of the galactoagglutinin family, is a vital gene in the regulation of the liver immune microenvironment and is significantly associated with increased risk of liver failure, cirrhosis, chronic active hepatitis B, and shorter survival time for hepatocellular carcinoma (HCC)." (PMID 37180150, 2023). "ALDH2, ITGB2, LGALS3, CTSB, PRDX1, and CD14 were identified as multifunctional proteins that are associated with tumorigenesis, damage, cancer cell death, necrosis, fibrosis, hepatocellular carcinoma, steatosis, and inflammation." (PMID 29481576, 2018). "In hepatocellular carcinomas, elevated serum or nuclear galectin-3 indicated histologic grade and vascular invasion; in this study both galectin-3 and Beclin1 are elevated in liver cancer when compared to normal tissues and possibly supports the relative resistance to chemo-radiotherapy." (PMID 22039439, 2011). "In multiple types of cancer including hepatocellular carcinoma (HCC), galectin-3 is highly expressed, and its level of expression is positively correlated with that of HK2 and PKM2 and negatively correlated with the prognosis of HCC patients." (PMID 36481721, 2022).
hepatocellular carcinoma (continued). "Hepatocellular carcinoma (HCC)‐secreted LGALS3 induces osteolytic bone metastasis (BM) via promoting osteoclast fusion and podosome formation." (PMID 33643786, 2021). "In addition, it was reported that galectin 3 can be used as a prognostic factor rather than a diagnostic marker in hepatocellular carcinoma." (PMID 32859099, 2020). "Up-regulation of Sema3A expression promoted tumor growth and tumor progression in a hepatocellular carcinoma (HCC) mouse model by enhancement of the expression of CapG, galectin-3, enolase 2 and Epithelial cell adhesion molecule (EpCAM)." (PMID 30696103, 2019). "We aimed to clarify if expression of galectin-3 is related to the clinicopathological characteristics and prognosis of hepatocellular carcinoma (HCC) patients, and to explore the possible mechanisms of galectin-3 in hepatocellular carcinoma." (PMID 25260879, 2014). "Among the prognostically characterized aging genes, EZH2, G6PD, LGALS3 and PSMD14 were significantly differentially expressed in hepatocellular carcinoma samples from the TCGA database." (PMID 37853322, 2023). "Finally, we analyzed galectin-3 expression and micro-vessel density (MVD) by immunohistochemistry (IHC) to find its correlation with angiogenesis in Hepatocellular Carcinoma." (PMID 25260879, 2014). "It has been suggested that the HBV-X protein produced by HBV in hepatocytes can transactivate the Galectin-3 promoter or upregulate Galectin-3 expression through the CREB/ATF-transcription pathway after HBV infection, and this phenomenon is more obvious in normal liver cells than in hepatoma cells." (PMID 37180150, 2023). "Recently, we demonstrated that disrupted galectin-3 expression in male mice leads to the development of nonalcoholic fatty liver disease (NAFLD) and hepatocellular carcinoma (HCC) with liver fibrosis." (PMID 22593713, 2012). "However, the relationship between Runx2, Galectin-3, EMT, and VM has not been studied in hepatocellular carcinoma (HCC)." (PMID 28264434, 2017).
renal fibrosis (46 papers, 2011 to 2025). A final common manifestation of a wide variety of chronic kidney diseases characterized by glomerulosclerosis and tubulointerstitial fibrosis. "This study utilized Lgals3−/‐ mice and demonstrated that Lgals3 deficiency alleviated CaOx crystal deposition and renal fibrosis." (PMID 39903812, 2025). "For instance, the inflammation and fibrosis biomarker Galectin-3 plays a causal role in both cardiac and renal fibrosis, representing a potential common element in both CKD progression and cardiovascular damage." (PMID 38255650, 2023). "Galectin-3 has been also linked to the development of renal fibrosis in animal models by regulating myofibroblast activation." (PMID 34884897, 2021). "Using a model of unilateral ureter obstruction, a recent study demonstrated that genetic disruption of the gene encoding galectin-3 attenuated renal fibrosis." (PMID 27089335, 2016). "Galectin-3 has been linked to the development of renal fibrosis in animal models and is inversely correlated with estimated glomerular filtration rate (eGFR) in humans." (PMID 27089335, 2016). "Later, during the recovery phase at two weeks, MCP-treated mice demonstrated reduced galectin-3 in association with decreased renal fibrosis, macrophages, pro-inflammatory cytokine expression and apoptosis." (PMID 21494626, 2011). "The growth factor TGF-β plays a key role in the progression of renal fibrosis by promoting myofibroblastic differentiation and galectin-3 has been implicated in this type of differentiation and extracellular matrix production in hepatic stellate cells." (PMID 21494626, 2011). "In addition, pathology staining and Western blot analysis found that overexpression of Lgals3 significantly increased renal fibrosis and inflammation response caused by CaOx crystal deposition." (PMID 39903812, 2025). "Galectin-3 (Gal-3) has been linked to the development of renal fibrosis in animal models." (PMID 34884897, 2021). "It was found that Lgals3 was highly expressed in CaOx crystal deposition and stimulated the activation of glycolysis during crystal deposition and renal fibrosis." (PMID 39903812, 2025). "Knockout or pharmacological inhibition of Lgals3 demonstrated a significant reduction of crystal deposition and renal fibrosis." (PMID 39903812, 2025). "This study indicates that Lgals3 plays a potential novel therapeutic target for the prevention of Calcium oxalate (CaOx) stone formation and subsequent renal fibrosis." (PMID 39903812, 2025). "Taken together, these results indicate that Lgals3 overexpression can promote CaOx crystal deposition and renal fibrosis." (PMID 39903812, 2025). "The current study found that FGFR4 was significantly increased and is essential for Lgals3‐mediated CaOx crystal deposition and the development of renal fibrosis." (PMID 39903812, 2025). "In CKD, galectin-3 serves as a prognostic biomarker linked to increased all-cause mortality and kidney disease progression, with urinary galectin-3 levels correlating with renal fibrosis and decline in eGFR." (PMID 41235339, 2025). "By reflecting underlying inflammatory and fibrotic pathways common to myocardial injury, renal fibrosis, endothelial dysfunction, and metabolic disturbances, galectin-3 integrates these pathologies into a unified concept of multisystem organ dysfunction." (PMID 41235339, 2025). "In conclusion, Twist1/galectin-3 signaling regulates macrophage plasticity (M2 phenotype) and promotes renal fibrosis." (PMID 35182235, 2022). "In animal experiments of acute renal failure, galectin-3 expression was markedly up-regulated, and galectin-3 from macrophages is considered as a major mechanism in renal fibrosis." (PMID 33800867, 2021). "In a mouse study, the downregulation of galectin-3 expression by treatment with modified citrus pectin lessened renal fibrosis, inflammation, and apoptosis." (PMID 34437403, 2021). "Galectin-3 is up-regulated in a mouse model of progressive renal fibrosis (unilateral ureteric obstruction)." (PMID 27089335, 2016).
renal fibrosis (continued). "MCP decreased renal mRNA and protein levels of galectin-3 at 14 days after FA injection, in concert with significantly improved renal fibrosis as assessed by reduced expression of multiple fibrotic genes." (PMID 21494626, 2011). "Knockout of Lgals3 markedly reduces the deposition of CaOx crystal and renal fibrosis in vivo." (PMID 39903812, 2025). "Moreover, depletion of Galectin-3+ macrophages has been shown to reduce renal fibrosis after unilateral ureteric obstruction." (PMID 39407295, 2024). "Twist1 regulates macrophage plasticity to promote renal fibrosis through galectin-3." (PMID 38371379, 2024). "Future studies will determine whether galectin-3 is associated with CKD by examining galectin-3 expression in fibrotic kidneys and its role in macrophage polarization and development of renal fibrosis." (PMID 35182235, 2022). "In addition to acting as a direct profibrotic agent, galectin-3 also mediates aldosterone-induced cardiac, vascular, and renal fibrosis." (PMID 34979958, 2022). "This study suggests that inhibiting Twist1 or its target galectin-3 could be a potential new therapeutic strategy to prevent or treat renal fibrosis." (PMID 35182235, 2022). "Moreover, several studies have postulated that macrophages are the major source of galectin-3 driving renal fibrosis through myofibroblast activation." (PMID 35008648, 2021). "We confirmed that UUO-induced renal fibrosis was decreased in Lgals3–/– mice." (PMID 33033277, 2020). "However, if the injury is persistent or repetitive, galectin-3 might promote inflammation and fibrosis, and the severity of renal fibrosis and tubular injury of renal transplant also depends on galectin-3 expression." (PMID 34437403, 2021). "Elevated Lgals3 interacted with PKM2 and promoted the expression of FGFR4 via H3K18la, thereby facilitating CaOx crystal deposition and the development of renal fibrosis." (PMID 39903812, 2025). "The results revealed that Lgals3‐mediated lactate generation promoted lactylation at H3K18, which contributed to FGFR4 expression, and promoted CaOx kidney stone formation and renal fibrosis." (PMID 39903812, 2025). "Furthermore, the downregulation of Galectin-3 transcription has been associated with a reduction in inflammatory cell polarization and a decreased secretion of the profibrotic factors such as Arg-1, CD206, IL-10, and TGF-β, resulting in diminished renal fibrosis." (PMID 39407295, 2024). "Taken together, these data indicate that myofibroblast CD248 induced pro-fibrotic phenotype switching of macrophages through galectin-3, and that macrophage CCL17 upregulated collagen expression of myofibroblasts thereby leading to renal fibrosis." (PMID 33033277, 2020). "Elevated Lgals3 interacted with PKM2 and promote the expression of FGFR4 via histone H3K18 lactylation, thereby facilitating CaOx crystal deposition and the development of renal fibrosis." (PMID 39903812, 2025). "Because galectin-3 plays a significant role in the activation of M2 macrophages and UUO-induced renal fibrosis, we were intrigued about the interaction between galectin-3 and CD248 in renal fibrosis." (PMID 33033277, 2020). "In an animal model of renal fibrosis, knocking-out the galectin-3 gene was found to decrease renal fibrosis without changing macrophage recruitment or macrophage proinflammatory cytokine profiles." (PMID 25180794, 2014). "The absence of galectin-3 might also be related to protection against renal fibrosis and consequently better renal outcomes among children with cSFK." (PMID 34066698, 2021). "Furthermore, over-expression of lncRNA Rpph1 related with DN-related factor galectin-3 (Gal-3) directly up-regulated inflammation factors like Mcp-1 and TNF-α and proliferation via Gal-3/Mek/Erk signaling pathway in MCs with low glucose, which may further lead to renal fibrosis." (PMID 32752143, 2020).